U6 (U6 spliceosomal RNA )
Synonyms: LOC124904972
Gene: Small nuclear RNA gene on chromosome 20 (35,769,785 to 35,769,867, reverse strand). Ensembl gene ENSG00000283527.
Gene Ontology:
Molecular function: U4 snRNA binding
Biological process: formation of quadruple SL/U4/U5/U6 snRNP; spliceosomal tri-snRNP complex assembly
Cellular component: U4/U6 x U5 tri-snRNP complex; U6 snRNP
Homologues: Orthologues: macaque U6 (96% identical), dog U6 (52% identical). Paralogues in human: RNU6-38P (84% identical), RNU6-476P (84% identical), RNU6-1145P (83% identical), RNU6-1158P (82% identical), RNU6-1323P (82% identical), RNU6-20P (82% identical), RNU6-310P (82% identical), RNU6-393P (82% identical), RNU6-438P (82% identical), RNU6-477P (82% identical), RNU6-574P (82% identical), RNU6-891P (82% identical), and 1286 more.